IDO1 (indoleamine 2,3-dioxygenase 1)
Diseases named in the same sentence as IDO1 in open-access papers (continued):
Sharing a sentence is not in itself a finding about the gene and the disease.
tumor (continued). "To evaluate the anti-tumor effect of the triple blockade of MEK, PD-L1 and Ido-1, we treated 5 established ex vivo cultures with atezolizumab, selumetinib, or epacadostat or their combination for 6 days." (PMID 36419183, 2022). "Mice were administered the IDO1 inhibitors, i.e., YH29407 (100 mg/kg, Q.D. or B.I.D.), epacadostat (100 mg/kg, B.I.D.), and BMS-986205 (100 mg/kg, Q.D.)when the mean tumor size reached 50 mm3." (PMID 36545214, 2022). "Next, we checked IDO1 mRNA expression in three sets of matched PDAC primary tumors vs. the corresponding normal pancreas and here too, the tumor samples clearly showed a significant up-regulation of IDO1 mRNA as opposed to normal pancreas." (PMID 35997090, 2022). "Indoleamine-2,3-dioxygenase 1 (IDO1) catalyzes the conversion of tryptophan into kynurenine which lead to an immune-suppressive TME and thus contributing to tumor growth." (PMID 36038935, 2022). "ROC analysis revealed that the expression of the IDO1 (p = 0.025) and LGALS9 (p = 0.024) genes had a statistically significant relationship with the degree of tumor differentiation." (PMID 36430322, 2022). "The IDO1/TDO dual inhibitors CB548 and CMG017 elicited a robust antitumor immune response and dampen tumor progression when combined with ICI." (PMID 35173722, 2022). "IDO-1 and IFN-G appear to have co-stimulatory roles, promoting the induction/expression of each other in tumor immunoevasion." (PMID 36612271, 2022). "This review elucidates the network of immunosuppressive mechanisms regulated by IDO1 in TME, which is involved in the process of tumor development." (PMID 35681736, 2022). "IDO1 can inhibit the function of CD8+ effector T cells and natural killer (NK) cells in the tumor microenvironment, mediating potent immunosuppressive effects in cancer." (PMID 36387196, 2022). "In summary, tumor reduction was observed after treatment with IDO1 inhibitors compared to the control group, where the novel YH29407 drug demonstrated the greatest anti-tumor effects." (PMID 36545214, 2022). "In the local tumor microenvironment, CTLA-4 expression in Tregs upregulates Ido-1 in DCs, which reciprocally promotes Treg activation." (PMID 36419183, 2022). "Some of these biomarkers are immunosuppressive or have pro-tumor activity such as PD-L1, IL17RE, LAG-3, IDO-1, TIM-3 whereas others have antitumor activity such as CD8+ T-cells, OX40, CXCL9 and others have a mixed role such as IFN-G." (PMID 36612271, 2022). "In tumor tissues, IDO2 contributed to IDO1-mediated immune tolerance and functioned as a negative regulator of IDO1 by competing with it for the heme binding site." (PMID 35045867, 2022). "At the same time, CD8 + T cells in the tumor microenvironment can produce IFN-γ, which in turn stimulates the up-regulation of PD-1/PD-L1 and IDO1 gene expression." (PMID 35875026, 2022). "IDO1-mediated TRP metabolism in the KYN pathway is one of the most widely studied metabolic pathways involved in immune tolerance and tumor cell immune evasion." (PMID 36163134, 2022). "Early studies indicated that IDO expression by tumor cells correlates with little or null T cell infiltration, and mice immunized with IDO1-expressing tumor cells fail to reject the tumor." (PMID 36713558, 2022). "In the tumor site, the inhibition of COX2 can down-regulate IDO1 expression and fall serum Kyn levels." (PMID 35918736, 2022). "Overall, however, the induction of IDO1 and pro-inflammatory cytokines by pro-carcinogenic serine proteases may represent a novel, additional mechanism of immunosuppression by invading microbes and tumour cells, raising the possibility that they should be considered targets for new drug development." (PMID 35371018, 2022). "This suggests that IDO1 knockdown and US-induced ICD activation coupled with LGG-activated immune response pathways together mediated systemic anti-tumor immunity." (PMID 36550159, 2022).
tumor (continued). "MDSCs, DCs and tumor cells have the capacity, by autocrine IFN-g release, to secrete indoleamine 2,3-dioxygenase 1 (IDO1), an enzyme that catabolizes tryptophan in kynurenine." (PMID 35406412, 2022). "The oxidative Trp metabolic rate-limiting enzymes, IDO1 and TDO2, have been demonstrated to be constitutively expressed at high levels and are responsible for tumor growth and metastasis in several tumor types." (PMID 36172162, 2022). "Overall, upregulating miR-760 can inhibit the apoptosis-promoting effect of IDO1 on CD8+, thus inhibiting tumor immune escape, which is a latent strategy for treatment and new drug development." (PMID 35872931, 2022). "Therefore, in tumor tissue performed bulk-seq, the infiltration of IDO1 macrophages may be accompanied by the infiltration of other immune cells, such as CD8+ T cells and M1 macrophages, resulting in H-IDO1M scores associated with immune infiltration and immunotherapy response." (PMID 36248886, 2022). "Tumor infiltrating dendritic cells (DCs), and TGF-β, IL-2, and indoleamine-2, 3-dioxygenase-1 (IDO-1) are all essential cells and molecules that promote CD4+ T-cell differentiation into Tregs." (PMID 35371055, 2022). "USP14 inhibition decreases IDO1 protein levels, reverses the immune tolerance of CRC tumors, and sensitizes CRC tumor cells to anti-PD-1 therapy." (PMID 36163134, 2022). "In this review, we present the proliferative role of 15 immune checkpoints, including PD1, PD-L1, FGL1, CD155, CD47, SIRPα, CD276, IDO1, SIGLEC-15, TIM3, Galectin-9, CD70, CD27, 4-1BBL, and HVEM, in tumor progression." (PMID 36358792, 2022). "Indoleamine 2,3-dioxygenase 1 (IDO1) and tryptophan 2,3-dioxygenase 2 (TDO2) play pivotal roles in cancer viability and motility, and they facilitate tumor cells escaping the host immune system by catalyzing the initial step of the Kyn production." (PMID 35406118, 2022). "In melanoma, in the tumor compartment, high expression levels of CD8, CD3, TIM3, IDO1 etc. suggested longer progression free survival (PFS), whereas high levels of B2M and PD-L1 in macrophage compartment were associated with longer overall survival (OS)." (PMID 36313703, 2022). "The immune-checkpoint genes PD-L1 (CD247), CTLA4, LAG3, TIM3 (HAVCR2) and IDO1 were assessed using gene expression data, with significantly higher expression of each in DDIR-positive tumours." (PMID 34728791, 2022). "The PRNMT is architected through self‐assembly of indoleamine 2,3‐dioxygenase 1 (IDO‐1) inhibitor modified small‐sized CuS nanoparticles (CuS5) and tumor microenvironment (TME) responsive cationized polymeric matrix." (PMID 36073839, 2022). "Small-molecule PROTACs for EGFR are demonstrated to decline IDO1 as well as PD-L1 in non-small cell lung cancer (NSCLC) cell lines and tumor tissues." (PMID 36080223, 2022). "IDO inhibitors are used as a method to reverse the immunosuppressive effect of regionally expressed indoleamine 2,3-dioxygenase 1 (IDO1) at the tumour site, which usually impedes T-cells maturation by interfering with the kynurenine pathway." (PMID 36230995, 2022). "Our study shows that Tyk2 prevents Ido1 expression in CRC cells and promotes CRC immune surveillance in the tumor stroma." (PMID 36185806, 2022). "Research found that combining select therapies with IDO1, LAG-3, and TIM-3 blockade tend to benefit against tumor growth." (PMID 36060266, 2022). "If this is true in our experimental system, decreased expression of IDO1 in carbidopa-treated PDAC cells would reverse this process resulting in stimulation of mTORC1 signaling, which would be favorable for tumor growth, an effect opposite of what we observed." (PMID 35997090, 2022). "Considering the importance of IDO1 and TDO2 inhibitors in tumor immunotherapy, we developed an extracellular inhibitor screening model." (PMID 35571116, 2022). "However, whether macrophages with high IDO1 expression affect tumor immunity remains unclear." (PMID 36248886, 2022).
tumor (continued). "In this study, we compared the anti-tumor effects of YH29407, the best-in-class IDO1 inhibitor with improved pharmacodynamics and pharmacokinetics, with first and second-generation IDO1 inhibitors (epacadostat and BMS-986205, respectively)." (PMID 36545214, 2022). "Usually, at the early stages of tumour progression, the production of immunosuppressive factors by tumours is poor, allowing high levels of IFN secreted by the CTLs or NK cells for IDO1/AhR activation." (PMID 34539663, 2021). "Conversely, the high activity of tumor suppressor protein Bin-1 was connected with low IDO1 expression and better prognosis for patients, which additionally links the TRP metabolite pathway with tumor development." (PMID 34071442, 2021). "Each CD44+ cell-type functions immunosuppression through different ways: CD44+ tumor cells express CD276, IL13, VEGFA, and IDO1; CD44+ TAMs express IL10, TGFB1, VEGFA, and HAVCR2; CD44+ T cells express CD274, TGFB1, CTLA4, LAG3, and PDCD1." (PMID 35187044, 2021). "Since Ido1 expression in CT26 and TME cells inhibits T cell anticancer immunity, its repression likely contributed to tumor clearance." (PMID 34578328, 2021). "The expression of IDO1 in the majority of cancers is related to immunosuppression, which promotes tumorigenesis, while the expression of TDO2 is responsible for tumor invasion and proliferation." (PMID 34943977, 2021). "IDO1 and TDO2 enzymes catalyze Trp oxidation to Kyn, which are frequently observed in tumor tissues and tightly correlated with the poor prognosis in patients." (PMID 34657635, 2021). "This study provides ideas for the application of IDO1 inhibitors in the treatment of CESC and explores the potential value to enhance anti-tumor immunity and immunotherapy." (PMID 34778035, 2021). "The use of IDO1 inhibitors as add-on therapy can also be effective in inhibiting IDO-induced angiogenesis and thus reducing tumor growth and metastatic potential." (PMID 34959693, 2021). "Indoleamine 2,3-dioxygenase 1 (IDO1) induces T cells immune suppression and Treg hyperactivation by l-tryptophan (Trp) depletion and kynurenine (Kyn) accumulation in the tumor microenvironment." (PMID 33653420, 2021). "At the same time, TGF-β1-induced IDO1 signalling in pDCs upregulates IFN-β, a potential facilitator of tumour dormancy." (PMID 34539663, 2021). "IDO1 expression can be downregulated by kushenol E (KS76, DL = 0.59, Caco-2 = 0.58) and kushenol F (KS74, DL = 0.61, Caco-2 = 0.45) to inhibit tumor proliferation and induce apoptosis." (PMID 34899291, 2021). "Regarding the expression of IDO-1 and IDO-2, several studies show that their role can influence tumor progression." (PMID 33671892, 2021). "In a mouse model of B16-OVA tumor cells implanted in FoxP3-GFP reporter mice, IDO1 inhibition led to increased IL-17 expression in Tregs cells suggesting that tryptophan and kynurenine metabolism play an important role in Th17/Treg plasticity in vivo." (PMID 33868263, 2021). "IDO1 inhibition by navoximod resulted in a significant decrease in KYN level and KYN/TRP ratio in tumor cells and plasma." (PMID 34201791, 2021). "Recent preclinical research on the AhR receptor (which is activated by immunosuppressive metabolites of tryptophan produced by IDO1) demonstrated that AhR blockade can reverse TME immunosuppression and synergise with ICB to reduce tumour growth." (PMID 34944851, 2021). "The first mechanism involves the overexpression of the rate-limiting enzymes IDO1 and TDO2 to deplete TRP within the tumour microenvironment." (PMID 34680327, 2021). "highlighted the importance of immune status in prognostication—PDL1 and B7-H4 on tumour cells and PDL1, B7-H3, B7-H4, IDO-1, VISTA, ICOS, and OX40 on intralesional immune cells." (PMID 34956172, 2021). "Compared to genetically engineered mouse model (GEMM) tumor tissue, tumor-derived primary KPC cells cultured under normal in vitro conditions displayed undetectable Ido1." (PMID 33831358, 2021).
tumor (continued). "IDO1 expression in CESC and paraneoplastic tissues was analyzed through TCGA database (306 tumor samples and 3 adjacent tumor samples) using Wilcox-tests in R software." (PMID 34778035, 2021). "We studied gene expression levels of immune-related genes PD-1, PD-L1, PD-L2, IDO-1, IDO-2 and INFγ in tumor tissue of surgically resected NSCLC and correlated the finding with clinicopathological features and patient outcomes." (PMID 33671892, 2021). "IDO1 and TDO expression was found in various cells in the TME (including metastatic sites) and tumor-draining lymph nodes, including tumor, stromal, vascular, and immune cells." (PMID 34943606, 2021). "Past studies showed that CXCL13, IDO1, PI3, SPP1 and TRIM22 were closely correlated with the prognosis, immunization and chemotherapy sensitivity of tumor." (PMID 34736480, 2021). "Consistent with the in vitro results, curdione down-regulated IDO1, ki67, and p62, and up-regulated the cleaved caspase-3, Beclin1 and LC3 in tumor tissues." (PMID 33718227, 2021). "CMG017 and CB548, two dual inhibitors of IDO1 and TDO2, have been shown to potently suppress the kynurenine pathway and they showed promising anti-tumor efficacy, with favorable pharmacologic profiles, overcoming resistance to immune checkpoint inhibitors." (PMID 33924971, 2021). "In mouse models of HCC, IDO1 blockade along with anti-CTLA-4 treatment proved a more effective means to reduce tumor growth than anti-CTLA-4 monotherapy, paving the way for IDO1 inhibitors to be tested in combination therapies." (PMID 34440865, 2021). "All the genes identified to activate the tumor microenvironment pathway were highly upregulated at day 93 PI except secreted phosphoprotein 1 (SPP1), Indoleamine 2,3-dioxygenase 1 (IDO1), UBD and CD274, which were also highly upregulated at day 45 PI." (PMID 34946170, 2021). "The IDO1 inhibitor has been shown to alleviate immunosuppression in the TME and promote the activation of tumor-specific T cells in preclinical models." (PMID 33546704, 2021). "On the other hand, IDO1 expression is positively correlated with tumor grade, suggesting prognostic value in HCC tumor progression." (PMID 34769098, 2021). "Compared with the paracancerous tissues, the expression of CXCL13(P = 0.0093), IDO1(P = 0.0068), PI3(P = 0.0161), SPP1(P = 0.0122) in tumor tissues was significantly increased, while TRIM22(P = 0.0342) was significantly decreased." (PMID 34736480, 2021). "In terms of LUAD patients, most biomarkers, including IDO1, CTLA4, LAG3, CD40, TNFRSF18, TIGIT, and TNFSF14, were significantly increased in tumor tissues with high B cell abundance compared with that of low B cell group." (PMID 34422829, 2021). "We then analyzed the coexpression of the QIF markers in the tumor compartment, as well as the coexpression of B7H3, IDO-1 and Galectin-9 in the stromal compartment due to their high positivity rate in this subarea." (PMID 35145510, 2021). "IDO-1 is a rate-limiting enzyme and can convert tryptophan into kynurenines, which is expressed on the surface of APC and epithelial-derived tumor cells." (PMID 34367975, 2021). "The tumor samples were stained for CD68 (total macrophage marker), CD163, CD206, CD204, CHID1 (M2 markers), inducible nitric oxide synthase (iNOS), IDO1 (M1 marker), FoxP3 (Treg marker), CD3 (mature T-cells marker), CD8, and PD-L1." (PMID 33466316, 2021). "Indoleamine-2,3-dioxygenase 1 (IDO1) has been intensively pursued as a therapeutic target to reverse the immunosuppressive cancer-immune milieu and promote tumor elimination." (PMID 34148865, 2021). "To verify our guess, we investigated tumor-related immune checkpoints, including CD273, CD274, CTLA-4, and the ones that were newly emerging, LAG-3, TIM-3, TIGIT, CD276, BTLA, and IDO1, between the two subgroups." (PMID 33558879, 2021).
tumor (continued). "Our efforts concentrated on developing an immune signature with prognostic ability based on the comprehensive list of immune-related genes (PD-1, PD-L1, PD-L2, IDO-1, IDO-2 and INFγ) and then examining gene expression in the tumor microenvironment." (PMID 33671892, 2021). "Aryl hydrocarbon receptor (AHR) was considered to be an important pan-tumor therapeutic target, but small molecule inhibitors targeting AHR target gene IDO1 have failed in clinical trials." (PMID 33692337, 2021). "By down-regulating the expression of IDO1, the HS donor induced T effector cells and inhibited MDSCs, and effectively restricted the tumor development of H22 HCC tumor-bearing mice." (PMID 34869376, 2021). "The tumor samples were stained for M2 marker CHID1 and M1 markers inducible nitric oxide synthase (iNOS) and IDO1." (PMID 33466316, 2021). "Novel therapies targeting inhibitory (e.g., IDO-1, LAG-3, TIGIT, TIM-3, VISTA) and stimulatory (e.g., ICOS, GITR, OX40, 4-IBB) proteins within the tumor microenvironment (TME) are under active investigation." (PMID 34093591, 2021). "Recent data indicate that IDO1 gene expression characterizes a poorly differentiated, more aggressive NMIBC, with IDO1 gene expression in tumor tissues directly correlating with tumor size (R (correlation coefficient) =0.24, p=0.04) and stage (R=0.25, p=0.03)." (PMID 33585182, 2020). "Importantly, the expression of IDO1 and TDO is controlled by the AhR and, when increased, causes depletion of local tryptophan pools in the microenvironment, suppression of antigen-specific T cell responses, and promotion of T regulatory (Treg) cell differentiation during tumor development." (PMID 32824193, 2020). "In a number of tumor cell lines, constitutive IDO1 expression depends on COX-2 and PGE2 which upon autocrine signaling through the EP receptor activates IDO1 via the PKC and PI3K pathways." (PMID 33271839, 2020). "And astragaloside IV can assist the anti-tumor effect of PD-1 by blocking the binding of GBP1 and IDO1." (PMID 33552086, 2020). "It suggests that IDO1, PD‐L1 and LAG3 were partially regulated by the same mechanism or inducer in tumour." (PMID 32227579, 2020). "IDO1 and NOX2 are known to exert a potent immunosuppressive effect in a variety of human solid tumors by reducing both tumor-infiltrating T cells as well as B cells." (PMID 32719800, 2020). "Further studies investigating the effects of IDO1, TDO, or KMO inhibition on tumor immune response should also take the impact on neurobehavioral manifestations into consideration." (PMID 32153576, 2020). "Indoleamine 2,3-dioxygenase 1(IDO1) enzyme is involved in the catabolism of the essential amino acid tryptophan and plays an important role in immune evasion and tumor growth through production of kynurenine." (PMID 33585182, 2020). "Moreover, such DNCaNPs upon administration could not only directly cause effective ICD of cancer cells and then elicit the host’s antitumor immunity, but also reduce the density of immunosuppressive Tregs inside TMEs by synergistically inhibiting IDO1 and neutralizing tumor acidity." (PMID 34138248, 2020). "Indoleamine 2,3-dioxygenase 1 (IDO1) is a tryptophan-degrading enzyme, and an important immune suppressive gene in dendritic cells of tumor-draining lymphoid organs." (PMID 32933162, 2020). "The results showed that after IDO1 and GBP1 were knocked down, tumor volumes were decreased, and the tumor volume was the smallest in the IDO1 and GBP1 group." (PMID 33552086, 2020). "In cancer patients, tumor cells produce TDO and IDO1, and both are equally capable of producing Kyn." (PMID 32153576, 2020). "Akin to IDO1, it has been suggested that TDO2 metabolism contributes to tumor immune evasion by Trp metabolism." (PMID 33261077, 2020). "Indoleamine 2,3-dioxygenase 1 (IDO1) is closely related to the over expression of many cancers, and is therefore a promising target for tumor immunotherapy." (PMID 33101032, 2020).